IQGAP1 (IQ motif containing GTPase activating protein 1)
Diseases named in the same sentence as IQGAP1 in open-access papers (continued):
Sharing a sentence is not in itself a finding about the gene and the disease.
glioblastoma (8 papers, 2008 to 2026). The most malignant astrocytic tumor (WHO grade IV). "Crucially, single-cell profiling and virtual knockout analysis revealed elevated disulfidptosis in glioblastoma astrocytes and identified IQGAP1 as a key driver that modulates gene networks governing the cell cycle and neuron-glia interactions." (PMID 42164521, 2026). "Though IQGAP1 has been heavily studied and a subject of several reviews and book chapters, its emerging role in glioblastoma has been limited to a few studies." (PMID 37228393, 2023). "In our experiments, Numb5 and Numb6 showed interactions with Cdc42, IQGAP1 and vimentin, a protein expressed in radial glial and glioblastoma cells." (PMID 21122105, 2010). "To gain a mechanistic understanding of the role of IQGAP1 in glioblastoma and how might Haldol affect IQGAP1 pathways, we performed mass spectrometry on immunoprecipitate (IP) complexes obtained by IQGAP1-specific antibodies from Haldol-treated and untreated U87 and LN18 GBM cell lysates." (PMID 37228393, 2023). "This cluster contained several genes well-known to be overexpressed in glioblastomas (IGFBP2, CHI3L1) and markers of glioblastoma cancer stem cells as well (CD133, IQGAP1)." (PMID 18492260, 2008). "IQGAP1 couples HA/CD44 to cytoskeletal functions in other cells: IQGAP1 promotes HA-induced migration and proliferation of fibroblasts and CD44-mediated adhesion of glioblastoma cells to HA-rich ECM." (PMID 37071417, 2023). "The observed IQGAP1+/Iba1+/nestin+ cells could represent a common ancestor for TAMs and GBM tumorigenic neural precursors and/or, probably, an interconvertible multipotent progenitor cell form of both kinds and/or glioblastoma amplifying cancer cells (GSCs or progenitor cells)." (PMID 28098764, 2017).
lung carcinoma (8 papers, 2014 to 2023). "The interaction of MAP4K3 and IQGAP1 was associated with poorer prognosis in lung cancer, indicating the importance of IQGAP1-mediated signaling." (PMID 34439095, 2021). "A LoVo cell line stably expressing an IQGAP1 shRNA (shIQGAP1-85), which we used previously in lung cancer cell lines, was also generated, and loss of IQGAP1 was confirmed by WB." (PMID 28739799, 2017). "Interestingly, PDGF increases IQGAP1 expression by downregulating IQGAP1-targeted microRNAs (miR-23b and miR-125a-5p), causing oncogenic overexpression of IQGAP1 in lung cancer." (PMID 37071417, 2023). "Iqgap1−/− mice showed higher levels of liver metastasis than Iqgap1+/+ mice when implanted with mouse colon and lung cancer cells." (PMID 34439095, 2021). "Other than Wnt signaling, MAP4K3, a member of the mitogen-activated protein kinase kinase kinase kinase (MAPK4) family, regulates lung cancer metastasis through IQGAP1." (PMID 34439095, 2021). "Taken together with our data, these observations suggest that IQGAP1 Tyr-1510 phosphorylation is likely to occur in some lung carcinomas in which MET is up-regulated." (PMID 33087447, 2020). "Collectively, the GLK-IQGAP1 complex and IQGAP1 Ser-480 phosphorylation are prognostic biomarkers and potential therapeutic targets for human lung cancer recurrence." (PMID 31640697, 2019). "GLK-induced cell migration and lung cancer metastasis were abolished by IQGAP1 depletion." (PMID 37488602, 2023). "Interestingly, EGFR inhibitors used to treat EGFR-activated lung cancer upregulate IQGAP1 expression, which correlates with increased vascular permeability." (PMID 37071417, 2023). "A better understanding of the different effects of IQGAP1 on epithelial vs. stromal cells could help identify better treatments for lung cancer patients." (PMID 34439095, 2021). "Several studies argue that IQGAP1 plays a role in lung cancer by facilitating Wnt signaling." (PMID 34439095, 2021). "In KEAP1-deficient lung cancer, RSPO3, the ligand that activates Wnt signaling, is upregulated due to the Keap1 deficiency and, along with its receptor LGR4, mediates cell migration and metastasis in an IQGAP1-dependent manner." (PMID 34439095, 2021). "Similarly, we documented in two malignant lung carcinoma cell lines with enhanced MET activation that IQGAP1 is constitutively phosphorylated exclusively on Tyr-1510." (PMID 33087447, 2020). "Consistently, GLK-IQGAP1 interaction and GLK-induced IQGAP1 Ser-480 phosphorylation are detectable in cancer tissues and metastatic cancer cells of human lung cancer patients; this interaction and IQGAP1 phosphorylation are correlated with poor survival of lung cancer patients." (PMID 31640697, 2019). "Therefore, inhibition of the binding of IQGAP1 and Dvl in the cytoplasm and preventing Dvl nuclear translocation, might be one of the strategies for the prevention and treatment of lung cancer." (PMID 25436461, 2014). "IQGAP1 was phosphorylated exclusively on Tyr-1510 under conditions with enhanced MET or c-Src signaling, including in human lung cancer cell lines." (PMID 33087447, 2020). "MS analyses of protein phosphorylation in mouse models of human lung cancers, including those with enhanced EGFR and MET signaling, have identified phosphorylation of Tyr-1510 on IQGAP1." (PMID 33087447, 2020). "Colocalization of IQGAP1 and DVL in the cytoplasm and nucleus positively correlates with poorer prognosis in patients with non-small cell lung cancer (NSCLC), the most common type of lung cancer, and increased lymph nodal metastasis." (PMID 34439095, 2021).
ovarian carcinoma (7 papers, 2008 to 2023). A malignant neoplasm originating from the surface ovarian epithelium. "IQGAP1 expression level seemed to be closely associated with the enhanced invasion and migration in ovarian cancer cell lines." (PMID 19036171, 2008). "In ovarian carcinomas, patients with a diffuse pattern of IQGAP1 expression at the invasion fronts showed a lower overall survival rate than those with a focal pattern." (PMID 34439095, 2021). "Inhibiting endothelin-1 receptor binding reduced ovarian cancer cell metastasis in vivo and impaired the expression of IQGAP1 and other invadopodia effectors in the metastasized tumors." (PMID 34439095, 2021). "Current literature investigating IQGAP1′s role in ovarian cancer, though very limited, suggest that IQGAP1 promotes ovarian cancer by upregulating cell migration, invasion, and metastasis." (PMID 34439095, 2021). "In spheroid cultures, levels of IQGAP1 increased during the differentiation of ovarian cancer stem cell-like cells (CSC-LCs), and enhanced the invasion properties of CSC-LCs." (PMID 34439095, 2021). "Consistent with high Rac1 activity, silencing of IQGAP1 expression in fibroblasts, osteosarcoma cells and ovarian carcinoma cells lead to unconstrained membrane protrusion and disrupted directional cell migration on fibrillar extracellular matrices." (PMID 24355937, 2013). "In this study, we examined the effects of IQGAP1 silencing on cell invasion and migration, and explored it as a therapeutic target for metastasis of human ovarian carcinoma cells." (PMID 19036171, 2008). "Collectively, these findings suggest that IQGAP1 plays an important role in the invasion and metastasis of ovarian cancer cells." (PMID 19036171, 2008). "These lines of evidence have suggested the functional linkage between IQGAP1 and ovarian cancer invasion." (PMID 19036171, 2008). "We used RT-PCR and Western blot analysis to characterize expression of IQGAP1 in three human ovarian cancer-derived cell lines SK-OV-3, HO-8910 and HO-8910PM." (PMID 19036171, 2008). "Here, we investigated the effect of IQGAP1-specific short hairpin RNA (shRNA) expressing plasmids on metastatic potential of ovarian cancer HO-8910PM cells." (PMID 19036171, 2008). "In the present study, we have shown that ovarian cancer cell line HO-8910PM, which expresses high levels of endogenous IQGAP1, showed extremely high invasive abilities through the reconstituted basement membrane Matrigel." (PMID 19036171, 2008). "We showed that a significant reduction in IQGAP1 expression can markedly inhibit the invasion and migration potentials of ovarian cancer HO-8910PM cells." (PMID 19036171, 2008). "In the present study, we selectively silenced IQGAP1 expression in human ovarian cancer cells by exploiting RNAi technology." (PMID 19036171, 2008). "We have reported that of IQGAP1 was a novel marker of poor outcome in patients with ovarian carcinomas." (PMID 19036171, 2008). "In ovarian carcinoma cells, HA stimulates CD44:IQGAP1 association." (PMID 37071417, 2023). "Further investigation into how IQGAP1 impacts ovarian cancer and strategies targeting IQGAP1-mediated signaling could lead to new, effective treatments for ovarian cancer patients." (PMID 34439095, 2021). "Since IQGAP1 can bind to ERα and increase ERα-dependent transcription, it is logical to hypothesize that IQGAP1 plays a role in ovarian cancer." (PMID 34439095, 2021). "IQGAP1 is a scaffolding protein and overexpressed in many human tumors, including ovarian cancer." (PMID 19036171, 2008). "To evaluate whether silencing of IQGAP1 contributes to the reduced invasive behavior of ovarian cancer cells, we examined the invasive potential of IQGAP1 shRNA transfectants using an in vitro Matrigel-coated invasion assay." (PMID 19036171, 2008).
ovarian carcinoma (continued). "In this report, the knockdown of IQGAP1 expression by RNAi can successfully reverse the malignant behaviors of ovarian cancer cells, implicating that IQGAP1 may be a new candidate of drug target for treatment of ovarian cancers." (PMID 19036171, 2008). "Thus, our results provide new evidence of the potential use of IQGAP1-targeted RNAi as a novel way to reduce tumor progression of patients with ovarian cancer." (PMID 19036171, 2008). "More importantly, we first demonstrated that knockdown of IQGAP1 also led to attenuated Matrigel invasiveness, suggesting that therapies targeting IQGAP1 activity may prove efficacious for treating ovarian cancer metastasis." (PMID 19036171, 2008). "Our findings support the hypothesis that IQGAP1 promotes tumor progression and identify IQGAP1 as a potential therapeutic strategy for ovarian cancer and some other tumors with over-expression of the IQGAP1 gene." (PMID 19036171, 2008). "Therefore, we will further investigate the effects of IQGAP1-shRNA plasmids by intravenous administration on ovarian cancer metastasis in animal models." (PMID 19036171, 2008). "We have also reported that IQGAP1 was overexpressed in ovarian adenocarcinomas compared with adenomas and borderline tumors and its expression significantly correlated with poor prognosis in patients with ovarian carcinomas." (PMID 19036171, 2008). "To assess the role of IQGAP1 in conferring invasive properties to cells derived from ovarian cancer, we first determined whether expression of endogenous IQGAP1 correlated with invasive and migratory ability by using an in vitro Matrigel assay and cell migration assay." (PMID 19036171, 2008). "To investigate the specific mechanism by which TBC1D2 promotes ovarian cancer progression, we studied at first if TBC1D2 modulates OC cell migration and invasion through regulating RAC1 and IQGAP1." (PMID 35574392, 2022). "However, the contribution of IQGAP1 to invasive properties of ovarian cancer cells remains unknown." (PMID 19036171, 2008). "Inhibiting IQGAP1 in ovarian cancer cells did not impact proliferation but reduced cell migration and invasion." (PMID 34439095, 2021). "However, the exact mechanisms by which IQGAP1 regulates invasion and metastasis of ovarian carcinomas have not yet been elucidated." (PMID 19036171, 2008).
prostate carcinoma (7 papers, 2014 to 2025). A carcinoma that arises from epithelial cells of the prostate gland. "Phosphorylated AKT has been shown to be a negative regulator of IQGAP1-mediated ERK activation in prostate cancer cells." (PMID 33846302, 2021). "Consistent with the known ubiquitous expression of IQGAP1, we detected it in all 4 commonly used prostate cancer cell lines." (PMID 25924234, 2015). "Having established IQGAP1 as a cholesterol-induced protein in PC-3 cells, we next examined its expression in other commonly-used prostate cancer cell lines." (PMID 25924234, 2015). "In agreement with a role in mediating metastasis, the level of IQGAP1 is higher in aggressive prostate cancer cells, PC-3 and DU145, which also express caveolin-1." (PMID 25924234, 2015). "Moreover, we show that knockdown of IQGAP1 or caveolin-1 in PC-3 cells abolished the hypercholesterolemia-induced metastasis from xenografts, indicative of their functional involvement in prostate cancer metastasis in vivo." (PMID 25924234, 2015). "Taken together, our data show that hypercholesterolemia promotes prostate cancer metastasis independent of the androgen pathway, in part by increasing IQGAP1 and caveolin-1." (PMID 25924234, 2015). "As there are no reports linking hypercholesterolemia or prostate cancer with IQGAP1, we went on to confirm this result in vitro and in vivo." (PMID 25924234, 2015). "Although IQGAP1 is thought to be ubiquitously expressed, its expression in prostate cancer cells has not been examined." (PMID 24352566, 2014).
colon carcinoma (6 papers, 2004 to 2024). "Localised disruption of E-cadherin-mediated cell–cell adhesion sites was recently observed in invasive human colon carcinoma cells and this disruption was associated with relocalisation of IQGAP1, a Rac1/Cdc42 effector molecule." (PMID 14735193, 2004). "Moreover, depletion of LGR5 or IQGAP1 from colon cancer cells decreases the amount of β-catenin at the plasma membrane and alters the formation of cortical actin." (PMID 37071417, 2023). "In contrast, IQGAP1 promotes HGF-stimulated colon cancer cell invasion, implying that the functions of IQGAP1 in HGF/MET signaling may be cell-dependent." (PMID 37071417, 2023).
multiple myeloma (6 papers, 2017 to 2025). "A similar mechanism was observed in multiple myeloma cells as well where SP1/EP300 complex promoted proliferation of cancer cells through modulating the transcription of IQGAP1." (PMID 35242497, 2022). "Quercetin inhibits IQ motif-containing GTPase activating protein 1 (IQGAP1) expression in multiple myeloma cells." (PMID 34381559, 2021). "Finally, IQGAP1 promotes VEGF-stimulated proliferation of myeloma cells, further implicating IQGAP1-mediated VEGF/VEGFR2 signaling in tumorigenesis." (PMID 37071417, 2023). "In multiple myeloma, SP1 and P300 form a complex that regulates the transcription of IQGAP1 and thus promotes tumor cell proliferation." (PMID 37599359, 2023).
neuroblastoma (5 papers, 2015 to 2024). Neuroblastoma (NB) is the most common solid, extracranial childhood tumor. "Interestingly, IQGAP1-AA was shown to be deficient in promoting neurite outgrowth in neuroblastoma cells compared to wild-type IQGAP134." (PMID 32051509, 2020). "IQGAP1 is phosphorylated by protein kinase C (PKC), an event that is involved in epidermal growth factor receptor activation, and phosphorylation on IQGAP1 serines 1441 and 1443 are known to regulate neurite growth in neuroblastoma cells." (PMID 29240845, 2017). "Additionally, overexpression of wild-type IQGAP1 has been found to facilitate neurite outgrowth in neuroblastoma cells." (PMID 39000261, 2024). "Phosphorylation by PKC between IQGAP1 GRD and CT domains at S1441 and S1443 regulates the actin cytoskeleton in neuroblastoma cells to promote neurite outgrowth." (PMID 29240845, 2017).
thyroid cancer (5 papers, 2020 to 2024). "The expression level of metastasis-associated lung adenocarcinoma transcript 1 (MALAT-1) and IQGAP1 are both increased in tissues of patients with thyroid cancer and thyroid cancer cells." (PMID 33996538, 2021). "ZC3H13 overexpressed thyroid cancer cells have elevated m6A levels of IQGAP1 mRNA." (PMID 38351022, 2024). "IQGAP1 promoted thyroid cancer and was largely expressed in the cytosol." (PMID 33498739, 2021). "In addition, Huang and colleagues indicated that the overexpression of MALAT1 and IQGAP1 is correlated with the proliferation and invasion of thyroid cancer cells." (PMID 32760219, 2020). "In addition, the overexpression of MALAT1 could increase the expression of acetyl-H4 histone in the IQ motif-containing GTPase-activating protein 1 (IQGAP1) promoter, which may promote the proliferation and invasion of thyroid cancer cells." (PMID 34778078, 2021).
triple-negative breast carcinoma (5 papers, 2020 to 2024). An invasive breast carcinoma which is negative for expression of estrogen receptor (ER), progesterone receptor (PR), and human epidermal growth factor receptor 2 (HER2). "For instance, ITGB4 promotes triple-negative breast cancer to resist DNA damage via TNFAIP2/IQGAP1/RAC1, and thus accelerates the drug resistance of tumor cells." (PMID 38831335, 2024). "The signaling scaffold oncoprotein IQGAP1 was identified as a classification and therapeutic biomarker in triple negative breast cancer (TNBC) cell lines." (PMID 37215640, 2023). "ITGB4 promotes triple-negative breast cancer (TNBC) drug resistance via TNFAIP2/IQGAP1/RAC1." (PMID 37787041, 2023). "IQGAP1 mediates RAC1 activation by TNFAIP2 and promotes triple-negative breast cancer (TNBC) drug resistance." (PMID 37787041, 2023). "For interest in understanding mechanism involved in the development of triple negative breast cancer (TNBC), we chose to further examine how IQGAP1 might influence BRCA1 because it is both a centrosome marker and is associated with TNBC." (PMID 32655836, 2020).
bladder cancer (4 papers, 2017 to 2023). "Downregulation of IQGAP1 associates with high grade bladder cancer and poor patient survival." (PMID 33498739, 2021). "IQGAP1 depletion increases tumor growth in vitro and in vivo via TGF-β signaling and is associated with a worse prognosis in bladder cancer patients." (PMID 36831467, 2023). "Although almost all studies have confirmed that IQGAP1 is an oncogene, IQGAP1 was reported as a tumor suppressor in bladder cancer, playing a completely opposite role compared with other cancers." (PMID 36831467, 2023). "On the other hand, IQGAP1 displays tumor-suppressive functions in bladder cancer, a theme that is supported by our analyses of another urinary cancer ccRCC." (PMID 33266355, 2020). "Mechanistically, IQGAP1 downregulation increases TGFβ signaling in bladder cancer." (PMID 33498739, 2021).
cervical carcinoma (4 papers, 2015 to 2024). A carcinoma arising from either the exocervical squamous epithelium or the endocervical glandular epithelium. "IQGAP1 was overexpressed in both the nasopharyngeal and cervical cancer biopsies than the normal tissues." (PMID 39073693, 2024). "The current study reports for the first time a comparative analysis of the expression pattern of AKT, IQGAP1, and MMP16 in HPV‐associated nasopharyngeal and cervical cancers." (PMID 39073693, 2024). "The mRNA levels for IQGAP1 in nasopharyngeal and cervical cancer tissues were significantly higher than the corresponding normal adjacent tissues (p < 0.001)." (PMID 39073693, 2024). "In another cellular context, we verified the inhibitory effects of miR-124 on IQGAP1 mRNA expression in human cervical cancer cells (HeLa cells; data not shown)." (PMID 26934121, 2016).